TNF (tumor necrosis factor)
Diseases named in the same sentence as TNF in open-access papers (continued):
Sharing a sentence is not in itself a finding about the gene and the disease.
infection (continued). "Previous studies showed that both tumor necrosis factor and interleukin-l could induce a remarkable increase in serum TG level during infection and inflammation process." (PMID 31824407, 2019). "A 10-fold increase in TNFα was observed when the child cleared infection, but the IFNγ secretion was either unchanged or decreased with increase in age indicating that the NK cells were either not activated or inhibited by certain receptors, which subsequently supressed IFNγ synthesis." (PMID 31396204, 2019). "The initial inflammatory response during infection usually leads to the release of proinflammatory mediators like TNF-α, IL-1, IL-6, and NO by classically activated macrophages, and these have been shown to play important roles in mediating early protection during infection." (PMID 31824512, 2019). "For instance, TNF-α triggers local containment of infection, and IL-6, as well as IL-1β, could reduce viral replication or increase antigen processing, thus promoting specific immune response." (PMID 31156641, 2019). "In addition, we found that infection with EIB202 induced the expression of TNF-α and IL-10 transcripts, which was further enhanced in zebrafish larvae infected with Δtrxlp." (PMID 31314784, 2019). "Three studies examined the effect of TNF-α-308 (rs1800629) on infection post-operatively." (PMID 31270721, 2019). "Likewise, factors secreted by innate immune cells, including IFN‐β and TNF‐α were elevated early after infection." (PMID 29762870, 2019). "Infection of mice with other hypervirulent Mtb strains, such as thosebelonging to the W-Beijing lineage, also results in a poor protective Th1-drivenimmune response distinguished by the low and temporal expression of IFNγ, TNFα, andiNOS." (PMID 31411311, 2019). "Cells were reactivated with tumor necrosis factor α (TNFα) 8 days post infection." (PMID 30940165, 2019). "Moreover, the mRNA expression level of TNF-α was elevated significantly from 1 to 6 h after infection, which was in stark contrast to that observed in the negative control group (p < 0.01)." (PMID 30736473, 2019). "Moreover, Ahr knockout mice had higher serum levels of TNF in the blood prior to and also during infection." (PMID 31749794, 2019). "Additionally, similar levels of secreted TNF upon infection with the respective mutants provided further proof for equal macrophage infectivity of these different V. cholerae strains." (PMID 31736941, 2019). "Thus, Mφ were required in order to observe a predominant secretion of IL-6 and TNF-α in response to PA, PB and ST infection, and CCL3 in response to PA." (PMID 31412039, 2019). "Importantly, in vivo experiments using the mousepox model showed that both TNF- and CK-blocking activities are important determinants of virulence and have complementary roles in the control of local inflammation during infection." (PMID 31877657, 2019). "Thus, during clearance of infection, the increase in IL-4 maintains goblet cell function and protects it against the increasing levels of TNF-α and IFN-γ." (PMID 30665337, 2019). "It was shown that tumor necrosis factor-alpha (TNF-α), a proinflammatory cytokine rapidly released upon infection or trauma, suppresses peroxisomal β-oxidation in rat hepatocytes and downregulates the expression of mRNAs encoding for peroxisomal proteins such as catalase and acyl-CoA oxidase." (PMID 31382586, 2019). "TNF-α levels were higher only for the Na and Pf mono-infection groups." (PMID 33604551, 2019). "The evaluation of the cytokine profile showed that MAYV induces a strong inflammatory response in early days of infection, mediated by cytokines TNF-α, IL-6 and INF-γ and chemokine MCP-1." (PMID 31050676, 2019). "Moreover, a recent report revealed that targeting TNF-α with an anti-feline TNF-α monoclonal antibody prevented infection in cats experimentally infected with FIPV." (PMID 31118053, 2019).
infection (continued). "A robust innate immune response was observed in S. aureus infected femurs, with abundant levels of pro-inflammatory cytokines IL-1α, IL-1β, IL-6, and TNFα detectable as soon as one day after infection, similar to what has been reported in other musculoskeletal infection models." (PMID 30978245, 2019). "Indeed, production of gamma interferon (IFN-γ), tumor necrosis factor (TNF), and interleukin-2 (IL-2) by CD4+ T cells has been associated with preerythrocytic protection following CPS immunization and natural infection." (PMID 30787114, 2019). "Similarly, TNF-α was significantly suppressed in mice administered alcohol 6 or 24 h prior to infection compared to mice administered alcohol 0.5 h prior to infection." (PMID 31821337, 2019). "TNF in serum was increased in infected patients, presumably as a response to the infection." (PMID 31092295, 2019). "The changes in the cellular composition of the inflammatory cell infiltrate (notably, the reduced eosinophil accumulation) during H99-α infection suggested that production of TNF-α by the transgenic strain modulated Th1/Th2 bias and Th1/Th2-associated cytokine production in the lungs." (PMID 31404168, 2019). "Moreover, this reduction rate was by more than 70% at 24 hpi or later, suggesting a decisive role of nsp2 in modulating the production of TNF-α and IL-1β during infection." (PMID 31561412, 2019). "Moreover, dysregulation of these functions can occur when production of TNFα increases in response to infection or injury." (PMID 31026287, 2019). "Moreover, B cells are required for another function, such as amplification of the IFN-γ response by T cells via a TNF-α-mediated mechanism during infection." (PMID 30602524, 2019). "Infection with pathogenic mycobacteria such as Mycobacterium tuberculosis or M. avium leads to production of active TGF-β, which blocks the ability of IFN-γ and TNF-α to inhibit intracellular replication." (PMID 30818784, 2019). "Three infections were considered serious, 1 in the anti-IL-6R group and 2 in the anti-TNFα group." (PMID 31261772, 2019). "We found that hosts responded differently to anthelmintic treatment depending on demographic factors (age and sex) and importantly, that the relationships between TNF-α production and infection status or demographics differed between the systemic (spleen) and local (MLN) scale." (PMID 31368489, 2019). "-Downregulation of IL-6, IL-1β, and TNF-α -Cotreatment with 0.005 mg/g epinecidin-1 decreased the mortality rate upon infection. - 7 days after P. aeruginosa ATCC 19660 and P. aeruginosa R infection, the survival rate is 88.4% - All untreated mice died within 72 h of infection." (PMID 31824449, 2019). "Moreover, this boosted NS3 cross-reactive response was characterized by enhanced TNF-α production compared to primary infection, which is potentially significant given the link between TNF-α levels and disease severity in humans." (PMID 31143185, 2019). "A reduced production of TNF-α or IL-1β is related with higher bacillary burden, while a reduced production in IL-17 has been related to lower migration of T cells to the site of infection, conducting to severe scenarios of infection." (PMID 31637222, 2019). "Albeit not statistically significant, the levels of G-CSF, IL-1α, MCP-1/CCL2, MIP-2/CXCL2 at day 1, G-CSF, KC, MCP-1, and MIP-2 at day 2, and IL-1α, IL-1β, IL-6, IL-10, MCP-1, MIP-2, and TNF at day 3 post-infection were 1.5–4.4-fold higher in SIRT3/5−/− than in SIRT3/5+/+ mice." (PMID 31632409, 2019). "In contrast, TNF-i therapy with CS was associated with concerns regarding infection, and TNF-i therapy without CS with concerns regarding non-responders and relapse." (PMID 31228955, 2019). "Tumor necrosis factor alpha (TNFα) is an inflammatory cytokine produced by all cell types but principally is synthesized and released by macrophages and other immune cells in response to infection and noxious stimuli." (PMID 31801287, 2019).
infection (continued). "A lack of IL-18/IL-18R signaling enhanced bacterial clearance, attenuated liver injury, decreased the production of pro-inflammatory cytokines (such as TNF-α), and decreased expansion of pathogenic TNF-producing CD8 T cells and NK cells following IOE infection." (PMID 31134081, 2019). "Analysis of the 58 DE genes commonly altered by the infection of either R. conorii or R. montanensis revealed the enrichment of genes involved in inflammatory response, cellular response to tumor necrosis factor (TNF), cellular response to lipopolysaccharide, immune response, among others." (PMID 31024862, 2019). "Tumor necrosis factor alpha (TNF-α) is a pro-inflammatory cytokine released by activated microglia in response to infection, neurological disease, or tissue damage, and has been found to increase the permeability of the BBB when studied during in vivo experimentation." (PMID 31394791, 2019). "While TNFα functions as a systemic inflammation cytokine and regulates the immune cell response, IL-8 is a chemokine produced mainly by macrophages within the CNS and serves as a chemoattractant, recruiting neutrophils to the site of damage or infection." (PMID 31044584, 2019). "This hypothesis is corroborated by the higher blood levels of TNFα before the onset of infection, which probably remained elevated from the previous parasitic challenges." (PMID 31815153, 2019). "Moreover, apoptosis induction, tight junction redistribution, and an increased inflammatory response—represented by TNF-α, IL-1β, and IL-6 secretion—was observed in co-cultures after infection and reversed by curcumin." (PMID 31569415, 2019). "Infection or reactivation of herpesvirus family members in humans is associated with the clonal expansion of activated γδ T cells, which show reactivity against infected cells through the production of IFN-γ and TNF-α to reduce viral replication." (PMID 30893756, 2019). "In addition to de novo expression of a number of immunological important cell surface molecules, including CD200, CD11a, CD11b, microglia produce several cytokines and chemokines such as IL-6, IL-10, TNF, and GM-CSF in TE and upon infection in vitro." (PMID 30873157, 2019). "On the other hand, the risk for severe infection does not change between treatment with anti-TNF agents alone and with a combination of anti-TNF agents and immunomodulators." (PMID 31025187, 2019). "With a depletion of GSH during infection or T2DM, this could cause NF-kB release and upregulate the production of IL-1, TNF-α, and IL-6—all inflammatory cytokines." (PMID 31888124, 2019). "Early after infection (Wk3+), TNFα producing monocytes were found to be more frequent in peripheral blood of cynomolgus macaques, and the frequency of TNFα positive monocytes at this time point correlated negatively with the amount of lung pathology (Spearman's rho = −0.5507, p = 0.0145)." (PMID 31736945, 2019). "We further checked the cell cytotoxicity upon infection with wt, ΔsteA, and compl strains to probe whether this difference in TNFα production was due to a difference in cell death." (PMID 31921113, 2019). "Finally, the cytokine TNF-alpha is frequently used as a marker of infection, especially in gastrointestinal disorders which often affect piglets at weaning." (PMID 31069239, 2019). "Thus, we examined the expression of IL-1β, IL-6, IL-8, and TNF-α in primary porcine alveolar macrophages (PAMs) during infection." (PMID 31363150, 2019). "DENV3 infection for 24 h significantly increased the release of TNF-α in the RBL-2H3 cells." (PMID 31110077, 2019). "These tissue cytokine profiles indicate a significant reduction in activated neutrophils and macrophages in mice who were administered alcohol 0.5, or 3 h prior to infection with the greatest suppression of GM-CSF, TNF- α, and IL-12/p40 observed when alcohol was administered 6 h prior to infection." (PMID 31821337, 2019).
infection (continued). "The mouse model of BCG-pleural infection was performed, then the pleural cavity cells of WT (wild type), tmTNF KI and TNF KO mice were recovered before and after infection, and the frequency of both CD3+CD11b+TCRαβ+ and CD3+CD11b+TCRαβ− myeloid cells was assessed by flow cytometry." (PMID 31787969, 2019). "Optical clearing methods have also been used to examine the effect of macrophage epithelial reprogramming on granuloma cellular structure in a Mycobacterium marinum-zebrafish model, as well as the heterogeneity in granuloma tumor necrosis factor expression observed in this infection system." (PMID 31292229, 2019). "Thus, we have shown, both in vitro and in vivo, that TFP suppressed the levels of the pro-inflammatory cytokines TNF-α and IL-6 in a state of abnormal infection." (PMID 30848296, 2019). "IFN-γ, IL-1β, and TNF-α are important cytokines related to infection and immunity." (PMID 32038632, 2019). "The elevated risk of infection in the anti-TNF group does not change, if we exclude any of the articles." (PMID 30658717, 2019). "Similarly, TNF-α was suppressed ~ 2-fold in mice administered alcohol 6 h prior to infection compared to mice administered alcohol 0.5 h prior to infection." (PMID 31821337, 2019). "IL1β and TNF-α regulate inflammatory responses in a variety of diseases and infections." (PMID 31002726, 2019). "The host macrophages are identified as the major cellular reservoirs of CHIKV during infection and this virus triggers robust TNF production in the host macrophages, which might be a key mediator of virus induced inflammation." (PMID 31031770, 2019). "Besides IFN-γ, antigen-specific T cells have also been reported to produce other cytokines like tumor necrosis factor-α (TNF-α) and interleukin-2 (IL-2) following infection and/or vaccination." (PMID 30921340, 2019). "Furthermore, we compared the TNF-α levels in plasma and examined the bacterial burden in blood, brain, lung, and liver samples obtained at 24 and 48 h after intravenous infection." (PMID 31482074, 2019). "H-1PV infection alone and in combination with both checkpoint inhibitors caused strong activation of CTLs, which was reflected by an increased number of CD8+GranB+ cells and increased release of granzyme B, IFNγ, and TNFα." (PMID 31192129, 2019). "Due to the central roles of these modulators in disease microenvironments we anticipate that this HIF/COX/TNF pathway may have important implications in conditions such as inflammation, infection and cancer." (PMID 31611882, 2019). "TNF and IFNγ had opposite effects on IL-6 production, with IFNγ neutralization resulting in a significant increase in IL-6, with concentrations similar to that of a primary Lm-gp61 infection." (PMID 29438281, 2018). "In addition, TNF-α (1043.78 ± 53.23 pg/ml) levels reached their peak at 24 h post-live Fn infection and substantially decreased." (PMID 29500439, 2018). "Contrary to our expectations, infection downregulated IL-1β, TNF-α, and IFN-γ mRNA expression in some cerebral regions, such as the OB and HC, particularly in the sham and GX mice, suggesting that strong regulatory mechanisms prevent inflammatory immune responses in these specific brain regions." (PMID 30515051, 2018). "In response to IV infection TNFα promotes the secretion of the antiviral cytokine families: type I, II, and III IFNs through upregulating RIG-I and toll-like receptor 3, Myeloid differentiation primary response 88 (MyD88), TIR-domain-containing adapter-inducing interferon-β (TRIF), and IRF7 genes." (PMID 30250466, 2018). "Surprisingly, sublethal infection with either Pmt2-expressing or Pmt2-deficient yeast cells did not change core body temperatures, despite the production of fever-inducing cytokines (e.g., tumor necrosis factor alpha [TNF-α], interleukin-1β [IL-1β], and IL-6) after infection." (PMID 29295913, 2018).
infection (continued). "The end result could activate bystander macrophages, which is essential to deal with infection, but, at the same time, miR-155 may limit the magnitude of the inflammatory response by preventing hyper-activation of the TNF-producing cells." (PMID 29467762, 2018). "Interestingly, infection upregulated TNF-α expression in the males of the intact, sham, and GX groups, generating a dimorphic pattern (P < 0.001)." (PMID 30515051, 2018). "Additionally, the quantities of TNF and IL-1β secreted into the tissue culture supernatant over a 24 h period following infection were comparable between genotypes." (PMID 29892302, 2018). "Interestingly, gonadectomy increased TNF-α mRNA expression in the uninfected mice of both sexes (P < 0.01), and infection in GX mice significantly downregulated its expression (P > 0.01)." (PMID 30515051, 2018). "Likewise, cholesterol-exposed THP1 macrophages failed both to produce TNF-α in response to Mtb and to clear the infection." (PMID 29593722, 2018). "Within the site of infection, CTLs control viral replication by targeting and inducing apoptosis of virus-infected cells via the secretion of perforin and granzymes as well as the ligation of death receptors on the infected cells by TNF, Fas ligand, and TRAIL." (PMID 30042762, 2018). "However, despite significant IFN-γ reduction in cardiac tissue, TNF-α expression was similar between WT and IL-4−/−, both in uninfected mice (NI WT vs. NI IL-4−/−, p > 0.17) and after infection (Inf WT vs. Inf IL-4−/−, p > 0.5)." (PMID 30622430, 2018). "In this approach, we infected mice with AdGOL and on day 2 post infection injected TNF i.v.." (PMID 30442932, 2018). "When assayed 24 hours post-operatively, lower mRNA levels of TNFα (P = 0.03), IL-12 (P = 0.02), T bet (P = 0.04), IL-23 (P = 0.02), RORγt (P = 0.05) and FOXP3 (P = 0.02) were also associated with the subsequent development of an infection." (PMID 30212506, 2018). "Infection with the fpt mutant strain elicited altered inflammatory cytokine secretion: F. tularensis SchuS4ΔfptB infection resulted in a 12-h delay in IL-1β secretion and a significantly reduced TNF-α response across all time points measured." (PMID 29311235, 2018). "A burst of necrotic bodies shortly after infection may trigger a pro-inflammatory response that can promote, anti-viral responses and secretion of TNF-α among other pro-inflammatory cytokines." (PMID 29707546, 2018). "A possible explanation for this might be that TNF-α is also an important negative regulator of erythropoiesis and this aspect might predominate at later stages of infection." (PMID 29497418, 2018). "Furthermore, EMB +NAC treatment resulted in further downregulation (three-fold decrease) and a significant decrease in the levels of TNF-α at both 8 and 15 days post-infection compared to untreated control category." (PMID 30258443, 2018). "With a few responders in each infection group, the serum concentrations of the cytokines TNF-α and of IL-10 showed significant differences between the groups ≥100 epg and 4–99 epg for TNF-α and between 4–99 epg and <4 epg for IL-10 (p ≤ 0.05) for each comparison." (PMID 30619332, 2018). "Furthermore, 4b protein significantly reduced the expression levels of pro-inflammatory cytokines induced by TNF-α in infected cells as compared to infection with Δ4b virus, reinforcing the potential of 4b protein to repress the NF-κB response." (PMID 29370303, 2018). "Protection during secondary infection was conferred by IFNγ- and TNFα-producing γδ T cells." (PMID 30538697, 2018). "Tip-DCs produce TNF and inducible nitric oxide synthase (iNOS)/nitric oxide (NO) before infection by Listeria monocytogenes, which results in an effective mechanism against infection; however, in some cases, this response has been related to tissue damage." (PMID 30297662, 2018).